CYP2R1 (cytochrome P450 family 2 subfamily R member 1)
Description:
A cytochrome P450 monooxygenase involved in activation of vitamin D precursors. Catalyzes hydroxylation at C-25 of both forms of vitamin D, vitamin D(2) and D(3) (calciol). Can metabolize vitamin D analogs/prodrugs 1alpha-hydroxyvitamin D(2) (doxercalciferol) and 1alpha-hydroxyvitamin D(3) (alfacalcidol) forming 25-hydroxy derivatives. Mechanistically, uses molecular oxygen inserting one oxygen atom into a substrate, and reducing the second into a water molecule, with two electrons provided by NADPH via cytochrome P450 reductase (CPR; NADPH-ferrihemoprotein reductase).
Tractability: Small molecule: a structure with a bound ligand is known; it has a binding pocket of medium quality; it belongs to a druggable protein family. Antibody: UniProt places it where antibodies can reach, with medium confidence; UniProt predicts a signal peptide or a membrane-spanning region. PROTAC: ubiquitination databases record sites on it; a small molecule that binds it is known.
Gene: Protein-coding gene on chromosome 11 (14,877,440 to 14,892,247, reverse strand). Ensembl gene ENSG00000186104.
Subcellular location: Endoplasmic reticulum membrane; Microsome membrane
Pathways (Reactome):
Metabolism: Vitamin D (calciferol) metabolism; Vitamins
Disease: Defective CYP27B1 causes VDDR1B
Gene Ontology:
Molecular function: D3 vitamins binding; heme binding; iron ion binding; protein homodimerization activity; vitamin D3 25-hydroxylase activity; oxidoreductase activity, acting on paired donors, with incorporation or reduction of molecular oxygen, reduced flavin or flavoprotein as one donor, and incorporation of one atom of oxygen; monooxygenase activity; oxidoreductase activity, acting on paired donors, with incorporation or reduction of molecular oxygen
Biological process: calcitriol biosynthetic process from calciol; vitamin D metabolic process; vitamin metabolic process; xenobiotic metabolic process; vitamin D biosynthetic process
Cellular component: cytoplasm; endoplasmic reticulum membrane
Genetic constraint (gnomAD): Loss-of-function variants: 40 observed, 46.76 expected, observed/expected ratio (o/e) 0.86, 90% interval 0.66 to 1.11. The upper end of that interval is the gene's LOEUF score, 1.11, which puts it in group 4 of 6, group 1 being the genes least tolerant of losing a copy. Missense variants: 605 observed, 631.95 expected, observed/expected ratio (o/e) 0.96, 90% interval 0.89 to 1.02. Synonymous variants: 234 observed, 231.68 expected, observed/expected ratio (o/e) 1.01, 90% interval 0.91 to 1.13.
Homologues: Orthologues: chimpanzee CYP2R1 (99% identical), macaque CYP2R1 (97% identical), pig CYP2R1 (93% identical), dog CYP2R1 (93% identical), rabbit CYP2R1 (93% identical), guinea pig CYP2R1 (90% identical), mouse Cyp2r1 (89% identical), rat Cyp2r1 (88% identical), tropical clawed frog cyp2r1 (72% identical), zebrafish cyp2r1 (67% identical). Paralogues in human: CYP2J2 (42% identical), CYP2U1 (41% identical), CYP2D6 (39% identical), CYP2F1 (37% identical), CYP2W1 (37% identical), CYP2A13 (36% identical), CYP2C18 (36% identical), CYP2C19 (36% identical), CYP2A7 (36% identical), CYP2C9 (36% identical), CYP2E1 (35% identical), CYP2A6 (35% identical), and 3 more.
Diseases named in the same sentence as CYP2R1 in open-access papers:
CYP2R1 is named in the same sentence as 108 diseases in open-access papers, as found by Europe PMC text mining. Sharing a sentence is not in itself a finding about the gene and the disease. The quoted sentences say what the papers report.
vitamin D deficiency (52 papers, 2013 to 2026). A nutritional condition produced by a deficiency of VITAMIN D in the diet, insufficient production of vitamin D in the skin, inadequate absorption of vitamin D from the diet, or abnormal conversion of vitamin D to its bioactive metabolites. "Collectively, our findings reveal a novel association between CYP2R1 rs2060793 and vitamin D deficiency with AMI risk in the Bangladeshi population, underscoring the interplay of genetic and metabolic determinants in the molecular pathogenesis of AMI." (PMID 42247388, 2026). "Conversely, the CYP2R1 rs10741657 A-allele was associated with vitamin D insufficiency, increased adiposity, and elevated hs-CRP levels, suggesting a genetic predisposition to both metabolic and inflammatory disturbances." (PMID 40710009, 2025). "According to a meta-analysis, the CYP2R1 gene encodes the most important enzyme in vitamin D metabolism, and its mutation is strongly linked to vitamin D deficiency." (PMID 38354201, 2024). "Two CYP2R1 mutation-related vitamin D deficiencies, namely c.367 + 1 G > A and c.768dupT, were reported in a cohort of 27 patients in Saudi Arabia, where there is a high rate of consanguinity." (PMID 39457152, 2024). "On the other hand, the minor allele A at rs10741657 of the CYP2R1 is associated with higher levels of plasma 25(OH)D levels and lower odds of vitamin D deficiency (OR 0.40; p=0.002) in this population." (PMID 37929021, 2023). "Specifically, CYP2R1 is downregulated in the extrahepatic and liver tissues in the obesity-induced mice model which causes vitamin D deficiency." (PMID 37184736, 2023). "In accordance to our findings, Zhu H. and colleagues revealed that participants with severe vitamin D deficiency (25(OH)D ≤25 nmol/l) showed a pattern of reduced methylation of CYP2R1, CYP24A1 and DHCR7 genes in comparison with controls (25(OH)D >75 nmol/L)." (PMID 36061943, 2022). "A meta-analysis of genetic polymorphisms indicated that CYP2R1 {an important metabolic enzyme in the synthesis of [1,25(OH)2D3] in the liver} mutations in humans are significantly related to vitamin D deficiency." (PMID 35592626, 2022). "Since only mutations in CYP2R1 result in severe vitamin D deficiency (serum 25(OH)D levels below 10 ng/ml), CYP2R1 is considered the most critical vitamin D-25-hydroxylase." (PMID 34950686, 2021). "We suggest that in mouse the CYP2R1 repression in the liver plays an important role in obesity‐induced vitamin D deficiency." (PMID 33210060, 2020). "The SNV’s in CYP2R1 rs10500804 and rs12794714 correlated with a lower levels of vitamin D, were also associated with risk to vitamin D insufficiency." (PMID 32834827, 2020). "In this study, we report for the first time the significant association between SNPs from GC (rs2282679 and rs7041), CYP2R1 (rs10741657) genes and 25(OH)D levels which clearly support their roles in vitamin D Insufficiency in Arab and South Asian populations." (PMID 25405862, 2014). "The significant associations between the GC (rs2282679 and rs7041), CYP2R1 (rs10741657) SNPs and 25(OH)D levels clearly support the idea of a role in vitamin D insufficiency in Arab and South Asian populations." (PMID 25405862, 2014). "The logistic regression analysis for vitamin D deficiency supports the strong associations of CYP2R1 SNPs, and rs12794714 showed the strongest association with vitamin D deficiency (P = 0.003, OR = 1.72, 95 % C.I.; 1.20–2.47)." (PMID 25085266, 2014). "Recent genetic studies have associated vitamin D deficiency with several candidate genes including Cytochrome P450, family 2, R, (CYP2R1), the group-specific component gene (GC) and 7-dehydrocholesterol reductase/NAD synthetase 1 (DHCR7/NADSYN1)." (PMID 25405862, 2014). "We also found two of the CYP2R1 SNPs (rs10500804 and rs12794714) to associate significantly with Vitamin D level in Arabs signifying their possible roles in vitamin D insufficiency in this population." (PMID 25405862, 2014).
vitamin D deficiency (continued). "In humans, genetic mutation in the CYP2R1 gene causes an inherited form of vitamin D deficiency and rickets in children, and genome-wide association studies have identified CYP2R1 gene variants as 1 of the key genetic determinants of low 25-hydroxyvitamin D (25-OH-D) levels." (PMID 35524739, 2022). "The aim of this study was to sequence three selected fragments of the CYP2R1 gene, corresponding to the substrate binding and metal-binding sites of CYP2R1, to investigate the contribution of genetic variations to increased risk of vitamin D deficiency." (PMID 34944511, 2021). "While positive associations were found for 3 SNVs in VDR (rs59128934, rs7965274 and rs2853564), 2 SNVs in CYP24A1 (rs56229249 and rs34043203) and 2 in CYP2R1 (rs12794714 and rs10500804), indicating that the presence of such variations increase risk to vitamin D insufficiency." (PMID 32834827, 2020). "Studies conducted in humans have shown that CYP2R1 is a good candidate for the enzymatic conversion of vitamin D3 to 25(OH)D3, since patients with a mutation in CYP2R1 have a deficiency of 25(OH)D3 and exhibit signs and symptoms of vitamin D deficiency and develop rickets." (PMID 30393837, 2019). "In our study, the reduced expression of the CYP2R1 gene in OSCC could be explained by vitamin D deficiency in patients with cancer, evidenced by literature, although vitamin D has not been quantified in these patients." (PMID 30532780, 2018). "To study the possible mechanisms whereby vitamin D deficiency worsens with increased severity of liver dysfunction, we measured hydroxylases protein levels of CYP2R1, CYP27A1 (key enzymes in vitamin D synthesis) and CYP24A1 (key enzyme in vitamin D degradation) in 94 out of 345 subjects." (PMID 27399065, 2016). "Moreover, the fact that two of the CYP2R1 SNPs (rs10500804 and rs12794714) and one GC SNP (rs1155563) were found to associate with Vitamin D levels exclusively in Arabs signify their role in vitamin D insufficiency within this population." (PMID 25405862, 2014). "Alternatively, increased expression of the VDR and CYP2R1 may result from a homeostatic response of BALF cells to counter the effects of vitamin D deficiency." (PMID 23826346, 2013). "Several researchers have evaluated the relation between genetic variants of CYP2R1 and vitamin D status among populations and have concluded that a robust correlation existed between specific polymorphisms on SNPs (rs10766197 and rs10741657) and risk of vitamin D deficiency." (PMID 34835935, 2021). "Reported associations between CYP2R1, GC, and VDR gene variants and the risk of vitamin D deficiency." (PMID 41340975, 2025). "In a meta-analysis study, CYP2R1 and CYP27B1 genes were shown linked with different anthropometric measures of obesity and vitamin D deficiency patients." (PMID 37184736, 2023). "The study of Xu X indicated that polymorphisms in CYP2R1-rs10766197 and DHCR7/NADSYN1-rs12785878 were associated with vitamin D deficiency in Uygur and Kazak ethnic populations, supporting a genetic effect on vitamin D status in minorities." (PMID 38124154, 2023). "The study concluded that genetic variation at several loci—rs2282679 in GC, rs12785878 near DHCR7, rs10741657 in CYP2R1, and rs6013897 in CYP24A1—have a noticeably elevated risk of vitamin D insufficiency." (PMID 36672957, 2023). "Since a growing number of studies report associations between vitamin D deficiency and ASD risk, our findings of predicted damaging variants in the CYP2R1 gene in ASD subjects is particularly relevant." (PMID 35663546, 2022). "The associations of CYP2R1, CYP24A1, and CYP27B1 gene polymorphisms with vitamin D deficiency in multiple population have been reported." (PMID 34484304, 2021). "A recent Mendelian randomization study has also shown that polymorphisms in vitamin D-related genes, CYP2R1 [rs10741657] and DHCR7 [rs12785878], were associated with LBW suggesting a causal link between maternal vitamin D deficiency and neonatal birth weight." (PMID 32548071, 2020).
vitamin D deficiency (continued). "We aimed at investigating the family‐based association between SNPs of CYP2R1 and CYP27B1 and vitamin D deficiency." (PMID 30993743, 2019). "We conducted three studies including case‐control study, family‐based study, and siblings study to investigate the associations between SNPs in CYP2R1 and CYP27B1 and vitamin D deficiency." (PMID 30993743, 2019). "In summary, these results indicate that in the mouse model of type 1 diabetes suppression of hepatic Cyp2r1 expression does not result in reduced hepatic vitamin D 25-hydroxylase activity and vitamin D deficiency." (PMID 35524739, 2022). "SNPs for DHCR7, CYP2R1 and GC-rs4588 genes were not statistically significantly associated to vitamin-D deficiency." (PMID 35256680, 2022). "For patients with vitamin D deficiency, recent studies have suggested that a genetic relationship between patients with VDR and CYP2R1 gene variants may be linked to the deficiency." (PMID 35629892, 2022). "Polymorphisms in CYP2R1 gene could influence vitamin D status in the general population, and CYP27B1 rs4646536 T allele has been shown to be associated with vitamin D deficiency in a family-based study." (PMID 33882819, 2021). "The presence of enzymes CYP2R1 and CYP27B1 and the detection of vitamin D receptor expression in testicular tissue as well as evidence for clinically relevant vitamin D deficiency in hypogonadal men suggested a prominent role of the testis in the metabolism of this vitamin." (PMID 34107893, 2021). "Different variants in the loci of the genes responsible for the synthesis, hydroxylation, and transport of vitamin D (such as DHCR7, CYP2R1, CYP24A1, and GC), as well as VDR gene polymorphisms may also be associated with the risk of vitamin D deficiency." (PMID 33330279, 2020). "Thus, we aimed at investigating the family‐based associations of SNPs in CYP2R1 and CYP27B1 with vitamin D deficiency." (PMID 30993743, 2019). "We were therefore interested to determine whether the strength of association between profound vitamin D deficiency and delayed sputum smear conversion differed according to genetic variation in VDR, DBP and CYP2R1." (PMID 26193879, 2015). "In addition, the vitamin D metabolizing enzymes (CYP2R1, CYP27A1, and CYP27B1) are also widely expressed in Leydig cells of the testis, and vitamin D deficiency may result in reduced hypogonadism." (PMID 40365228, 2025). "We originally hypothesized that genetic polymorphisms associated with vitamin D deficiency would increase the risk of T1D, however, our results indicated that CYP2R1 (rs1993116) was not related to 25(OH)D levels, but was significantly associated with T1D." (PMID 36275052, 2022). "Different variants in the loci of genes (such as DHCR7, CYP2R1, CYP24A1, and GC) that are responsible for vitamin D synthesis, hydroxylation, and transport, as well as VDR gene polymorphisms, may be associated with the risk of vitamin D deficiency." (PMID 33330279, 2020). "However, rs12794714, the CYP2R1 SNP that consistently showed the strongest association with serum 25(OH)D levels and vitamin D deficiency in our AA subjects, was not the most strongly associated SNP in either GWAS meta-analyses." (PMID 25085266, 2014).
Obesity (30 papers, 2019 to 2025). Accumulation of substantial excess body fat. "The objective of this study was to determine the association between obesity and methylation of vitamin D-dependent genes (i.e., CYP2R1 and CYP27B1)." (PMID 37184736, 2023). "In another study, mutated CYP2R1 gene has been shown as linked to obesity and type 2 diabetes mellitus." (PMID 37184736, 2023). "There are few reports in the literature indicating that CYP2R1 is associated with metabolic outcomes, such as obesity, hypertension, and diabetes, which are important conditions related to MS." (PMID 36364874, 2022). "Studies in mice showed that obesity inhibited the expression of CYP2R1 in mouse livers, which was linked to a decrease in enzyme 25-hydroxylation activity, influencing fluctuations in the levels of 25-OH-D in the blood." (PMID 36532520, 2022). "Not only the expression level but also activity and genetic variants of liver Cyp2r1 are important factors in vitamin D metabolism, therefore, further studies focused on the role of 25-hydroxyases in obesity are needed." (PMID 32549901, 2020). "We therefore suggest that obesity represses CYP2R1 expression in human adipose tissue, and weight loss recovers the level of expression." (PMID 33210060, 2020). "The genotypic model confirmed a higher risk of COPD in patients with obesity (p = 0.017), overweight (p = 0.015), smokers (p = 0.016), former smokers (p < 0.001), and carriers of the CYP2R1 rs10741657-AA genotypes (p = 0.028) and CYP27B1 rs4646536-AA (p = 0.004)." (PMID 39583968, 2024). "However, a study has shown that gastric bypass surgery, which causes weight loss, can increase CYP2R1 expression in subcutaneous adipose tissue, indicating a potential recovery from suppression caused by obesity." (PMID 38179344, 2023). "For instance, in individuals with diabetes or obesity, the expression of CYP2R1—the enzyme responsible for vitamin D 25-hydroxylation—is suppressed, leading to decreased 25(OH)D levels despite stable overall vitamin D levels." (PMID 40768409, 2025). "In obesity, liver CYP2R1 mRNA expression and protein levels are reduced by 40% and 50%, respectively, leading to a 70% decrease in 25‐hydroxylase activity (p < 0.01) and ~20% lower serum 25‐hydroxyvitamin D (25OHD) levels." (PMID 40831018, 2025). "Specifically, levels of CYP2R1, the major hepatic 25-hydroxylase, were significantly reduced in mice with obesity." (PMID 38732514, 2024). "Studies have reported that obesity due to a high-fat diet leads to decreased hepatic CYP2R1 mRNA abundance and decreased 25(OH)D conversion." (PMID 38179344, 2023). "The main enzyme responsible for converting vitamin D to its active form, CYP2R1, is suppressed by obesity." (PMID 38179344, 2023). "We recently reported that fasting, as well as obesity-induced diabetes, in mice repress Cyp2r1, the major vitamin D 25-hydroxylase, in the liver through PGC-1α/ERRα and GR pathways." (PMID 35524739, 2022). "Previous results have shown that HFD-induced obesity significantly represses Cyp2r1 in the mouse liver." (PMID 35524739, 2022). "In our previous studies in the mouse model of HFD-induced obesity and type 2 diabetes, the plasma 25-OH-D decreased consistently with the lower hepatic Cyp2r1 level." (PMID 35524739, 2022). "In the current study, we utilized adipose tissue samples from morbidly obese patients pre‐ and postgastric bypass surgery to show that obesity also affects CYP2R1 expression in humans." (PMID 33210060, 2020). "In humans, weight loss induced by gastric bypass surgery increased the expression of CYP2R1 in the s.c. adipose tissue suggesting recovery after the obesity‐induced suppression." (PMID 33210060, 2020). "Obesity induced by HFD significantly repressed the CYP2R1 mRNA levels in the kidneys of both the male and the female mice by 51%, and 58%, respectively." (PMID 33210060, 2020).